MTOR (mechanistic target of rapamycin kinase)
Diseases named in the same sentence as MTOR in open-access papers (continued):
Sharing a sentence is not in itself a finding about the gene and the disease.
melanoma (continued). "Importantly, a very similar shift in the mTOR subcellular localization was also observed in two human melanoma cell lines expressing mutated NRAS, MEL-JUSO and SK-MEL-30." (PMID 32531927, 2020). "Whether proline synthesis is associated with regulation of the mTOR pathway in melanoma cells is controversial." (PMID 33083024, 2020). "Importantly, it has been reported that nonsynonymous mTOR mutations are frequent and likely predict a worse prognosis in melanoma patients." (PMID 30795533, 2019). "In this study, we show that BRAFV600E melanoma cells undergoes a reversible mRNA translational reprogramming, by upregulating a subset of mRNAs that encodes epigenetic regulators and mammalian target of rapamycin (mTOR) pathway-related proteins." (PMID 31844050, 2019). "This may be linked to possible activating mutations in mTOR, and these mutation-specific influences should also be considered in the context of improving the outcomes of patients with melanoma by using everolimus treatment." (PMID 28793923, 2017). "Clinical trials with PI3K/AKT/mTOR pathway inhibitors may be beneficial for melanoma patients with specific mTOR mutations." (PMID 29214525, 2017). "Although the NRF2 mutational status is not determined in the melanoma lines used, it would be interesting to determine whether mTOR-dependent growth sensitivity of melanoma cells to ROS-inducing agents is related to NRF2 mutation status." (PMID 25749517, 2015). "Our results suggest that inhibitor combinations targeting the MAPK and PI3K/AKT/mTOR pathways downstream of NRAS may be a potential treatment option for non-melanoma tumors harboring activating NRAS mutations." (PMID 25277205, 2014). "Indeed, the PI3K/AKT/mTOR pathway is aberrantly activated in up to 70% of melanomas and has been implicated in tumor progression and chemoresistance." (PMID 22535842, 2012). "Notably, the differentially expressed m1A-modified genes were associated with multiple melanoma-related pathways, including DNA replication, mTOR/AMPK signaling and melanin synthesis, suggesting a regulatory role of m1A modification in the pathogenesis of ocular melanoma." (PMID 38118002, 2024). "Therefore, we concluded that the AKT/PI3K/mTOR pathway was an extremely important signaling axis, promoting cell proliferation, migration, and stemness, which contributed to BRAFi resistance in V600E mutated melanoma." (PMID 36700470, 2022). "In a Chinese cohort of 412 melanoma patients, nonsynonymous MTOR mutations were found by NGS analysis in acral, mucosal, cutaneous melanomas (with and without chronic sun-induced damage), and unknown primary subtypes, with a frequency of 11.0, 14.3, 3.4–6.7, and 11.1%, respectively." (PMID 32850962, 2020). "Interestingly, melanoma patients with MTOR mutations often have shorter survival rates, suggesting that these mutations may lead to worse prognosis of the disease." (PMID 30166456, 2018). "MSCs derived from the umbilical cord prevented growth and diminished the level of mTOR in melanoma cells." (PMID 41346764, 2026). "In the same way, inhibition of mTOR (rapamycin and everolimus) had a significant impact on cell cycle, cell proliferation, and invasive potential of human melanoma cell lines." (PMID 41492362, 2026). "Following treatment with BA and BE, the expression levels of p-MAPK, p-PI3K, p-AKT, and p-mTOR exhibited a dose-dependent decrease, suggesting that regulation of autophagy-related pathways may represent a potential mechanism underlying the anti-melanoma effects of BA and BE." (PMID 41596235, 2026). "Inhibiting this cascade relieves mTOR suppression, thereby promoting autophagy and apoptosis in melanoma cells." (PMID 41596235, 2026). "In vivo assays further confirmed that BA significantly suppressed melanoma growth in C57BL/6J mice by blocking the PI3K/AKT/mTOR and MAPK pathways." (PMID 41596235, 2026).
melanoma (continued). "The activities of two metalloproteinases, MMP-2 and MMP-9, were studied in the primary WM3211 and metastatic Mel-1359 and MEWO melanoma cell lines after 24 h and 48 h treatment with mTOR inhibitors and their combinations." (PMID 40869090, 2025). "Our findings indicated that salidroside directly downregulated the gene expression involved in melanin synthesis and suppressed the growth of melanoma by inhibiting PI3K/Akt/mTOR pathway." (PMID 40708947, 2025). "Wogonin radically changed the NF‐kB/ERK/PI3K/Akt/mTOR signaling pathway in the case of melanoma to activate its anticancer effects." (PMID 41164269, 2025). "CC-115, a dual inhibitor of mTOR and DNA-PK, enhanced radiosensitivity in melanoma by blocking DSB repair." (PMID 40867277, 2025). "Previous studies have shown that melanoma cell proliferation is associated with the AKT, PI3K, mTOR pathways at the protein level." (PMID 40092985, 2025). ",58, 59, 60, 61, 62, 63 Previous studies have also examined inhibitors of PI3K, AKT, and mTOR signaling in canine tumors, including hemangiosarcoma, lymphoma, mast cell tumor, melanoma, mammary gland tumor, and OS." (PMID 41106249, 2025). "In 3-D melanoma constructs, fisetin inhibits the growth of human melanoma A375 cells by directly binding to p70S6K and mTOR." (PMID 40932870, 2025). "Fourteen overlapping targets (GSK3B, MAPK1, HSPA8, VEGFA, FGF2, MTOR, and so on) were considered potential targets for the treatment of melanoma with salidroside." (PMID 40708947, 2025). "This study aimed to explore the effect of salidroside on PI3K/Akt/mTOR in melanoma, which plays a role in regulating melanogenesis." (PMID 40708947, 2025). "Methyl wogonin has demonstrated strong anticancer effects on melanoma cells (A375) by the activation of increased DNA damage, apoptosis, decreased cellular invasion, and mTOR/PI3K/Akt signaling pathway modification." (PMID 41164269, 2025). "TIG1 suppresses melanoma cell growth and proliferation by inhibiting the mTOR signaling pathway and inducing endoplasmic reticulum stress, which promotes cell death and exerts an anti-tumor effect." (PMID 40699636, 2025). "The integrins activate Src-YAP1, thereby conferring dual resistance to MAPK and PI3K/mTOR inhibitors to melanoma cells." (PMID 40243917, 2025). "The PI3K/AKT/mTOR pathway is also one of the main transduction pathways that undergo uncontrolled activation in melanoma cells." (PMID 41373567, 2025). "The obtained results showed that salidroside decreased the percentage of mTOR-positive B16F10 melanoma cells." (PMID 40708947, 2025). "Research is focusing on the role of CD133-dependent activation of the PI3K/mTOR pathway in melanoma stem-like cells, which contributes to drug resistance and tumor recurrence." (PMID 40867277, 2025). "PI3K, AKT, and mTOR have been shown to be overactive across various cancer types, including melanoma." (PMID 39941158, 2025). "The mTOR/4EBP-1 axis is highly relevant for human melanomas, as shown by analysis of The Cancer Proteome Atlas, representing immunohistochemical stainings of 354 human melanoma samples." (PMID 40918647, 2025). "In this setting, pro-survival autophagy inhibitors, able to block autophagosome or autolysosome generation, and pro-death autophagy inducers, modulating mTOR-related and unrelated autophagic mechanisms, have proved to be useful against melanoma." (PMID 40721981, 2025). "Dysregulation of mTOR contributes to enhanced survival and the invasive potential of melanoma cells, and it represents an attractive therapeutic target." (PMID 40869090, 2025). "Together with the inactivation of AKT, mTOR, and MEK1/2-ERK1/2, activation of the CD95 death receptor and autophagy caused dysfunctional mitochondria, leading to pronounced melanoma cell death." (PMID 39935431, 2025).
melanoma (continued). "Targeting BRAFi + MEKi–tolerant cells that overexpressed NR2F1 using the mTOR inhibitor rapamycin delayed melanoma regrowth and the emergence of resistance." (PMID 40955663, 2025). "The combination of PTX and NCTD suppresses melanoma progression through dual mechanisms: inhibition of PI3K/AKT/mTOR signaling and promotion of tumor cell differentiation." (PMID 40806647, 2025). "A trial combining the PI3K/mTOR inhibitor voxtalisib (SAR245409) with the MEK inhibitor pimasertib (NCT01390818) reported a complete response in one melanoma patient." (PMID 40399946, 2025). "As a result of treating melanoma cells with combinations of mTOR/PI3K inhibitors with AS-703026 (MEK1/2 inhibitor), significantly stronger morphological changes were observed." (PMID 40869090, 2025). "GNAI1, ADCY1 and NR6A1 common target genes involved in the restriction of cAMP signal transduction and of the activation of mTOR pathway signaling were identified among the target genes in the lipid metabolism pathways dysregulated in resistant melanoma cells." (PMID 41550951, 2025). "An important piece of information from our study is the synergistic effect of combining mTOR/PI3K inhibitors with MEK1/2 blockades, especially in NRAS-mutated melanoma, where reciprocal activation limits the efficacy of monotherapy." (PMID 40869090, 2025). "The convergence of the renin–angiotensin system onto the Ras/RAF/MAPK/ERK and PI3K/AKT/mTOR pathways in melanoma presents exciting research avenues for therapeutic interventions." (PMID 39941158, 2025). "Mutations in BRAF, NRAS, NF1, and KIT drive overactivation of the Ras/RAF/MAPK/ERK and PI3K/AKT/mTOR signaling pathways, promoting melanoma progression." (PMID 39941158, 2025). "We observed a significant change in the distance and maximum speed of MEWO melanoma cells after treatment with mTOR and MEK1/2 kinase inhibitors." (PMID 40869090, 2025). "Recent studies have shown that SIN inhibits proliferation and promotes apoptosis in melanoma B16F10 cells via PI3K/Akt/mTOR-dependent autophagic pathway." (PMID 40932870, 2025). "This study demonstrated that celastrol affects B16-F10 melanoma cells by inhibiting the PI3K/AKT/mTOR signaling pathway and the expression of HIF-α mRNA, indicating that celastrol inhibits B16-F10 melanoma cell migration and survival." (PMID 38771435, 2024). "Flavokawain B, a chalcone, induces ROS-mediated autophagy in melanoma A375 cells by inhibiting mTOR, increasing LC3-II levels, and dysregulating Beclin 1/Bcl-2 levels." (PMID 39371094, 2024). "Sasanquasaponin III is a triterpenoid saponin obtained from Schima crenata Korth that induces autophagy in melanoma A375 cells by Akt/mTOR/p70 ribosomal S6 kinase (p70S6K) pathway inhibition, ROS accumulation, and LC3-II expression upregulation." (PMID 39371094, 2024). "HOTAIR leads to melanoma cell growth and metastasis by sponging miR‐152‐3p and activating the PI3k/Akt/mTOR signalling pathway." (PMID 38193829, 2024). "In summary, this study demonstrates that the molecular mechanism of celastrol in the treatment of B16-F10 melanoma cells involves the inhibition of HIF-1α mRNA expression by regulating the PI3K/AKT/mTOR signaling pathway." (PMID 38771435, 2024). "Conjunctival melanoma is closely associated with malignant melanoma that arises in sun-exposed skin and is characterized by the activation of the MAPK (RAS/RAF/MEK/ERK) or PI3K/AKT/mTOR pathways." (PMID 39223654, 2024). "While the PI3K/AKT/MTOR pathway plays a pivotal role in melanoma cell survival and proliferation, another critical aspect of melanoma progression is the deregulation of the cell cycle." (PMID 39200315, 2024). "In melanoma patients, the level of phosphorylated AKT (p-AKT) level is high, and the PI3K/AKT/mTOR pathway is activated due to PTEN loss." (PMID 39349424, 2024).
melanoma (continued). "The transition of RGP into VGP has been reported to be mostly associated with AKT activation, since the occurrence of melanoma metastasis is frequently associated, to a large degree, with AKT/mTOR activities." (PMID 38334632, 2024). "Rapamycin promotes autophagy in melanoma cells by blocking the mTOR pathway and increasing the protein levels of Bcl-2, Bax, and LC3-II." (PMID 39371094, 2024). "Although the role of the PI3K/Akt/mTOR pathway in regulating melanoma ferroptosis has been elucidated, its upstream signals remain enigmatic." (PMID 39135915, 2024). "Piezo1 ion channel protein can regulate calcium concentration in melanoma cells, further increasing the activation level of the PI3K/Akt/mTOR pathway, thereby regulating the malignant progression of melanoma." (PMID 38690080, 2024). "Another combination of hydroxychloroquine and temsirolimus is responsible for inducing autophagy through the mTOR pathway and cancer cell death in human melanoma." (PMID 39371094, 2024). "HOTAIR increases the development and spread of melanoma cells by absorbing miR-152-3p, thereby triggering the PI3k/Akt/mTOR signaling cascade." (PMID 39777348, 2024). "USP22 inhibition, PI3K inhibitor (GDC‐0941), Akt inhibitor (MK‐2206), and mTOR inhibitor (AZD‐8055) strongly inhibited melanoma invasion in melanoma cells." (PMID 39135915, 2024). "The present study further suggests that high expression of p62 and DYRK3 in melanoma can promote cancer growth via the mTOR pathway." (PMID 38519031, 2024). "In fact, our data indicate that RUNX2 induces the expression of CXCR4, which in turn promotes autophagy, cell invasiveness, and osteotropism, by inhibiting the mTOR signalling pathway in melanoma cells." (PMID 38474372, 2024). "Baicalein and baicalin suppress melanoma cell glucose consumption and metabolism via the mTOR-HIF-1α signaling pathway, resulting in anticancer effects." (PMID 38398617, 2024). "The following section will delve into the PI3K/Akt/mTOR signaling pathway and its implications in melanoma biology." (PMID 39200315, 2024). "Our data indicate that the RUNX2 transcription factor promotes the expression of the CXCR4 chemokine receptor on melanoma cells, which in turn promotes autophagy, cell invasiveness, and osteotropism, through the inhibition of the mTOR signalling pathway." (PMID 38474372, 2024). "For instance, it regulates the mechanistic target of rapamycin (mTOR) signaling pathway and promotes tumor growth in melanoma cells." (PMID 38103190, 2024). "Apoptosis, cell migration suppression, cell cycle arrest, and mTOR/PI3K/AKT pathway targeting were shown to be effective anticancer actions of kaempferol on A375 human melanoma cells." (PMID 38398617, 2024). "NVP-BEZ235 (Dactolisib), a dual PI3K/mTOR inhibitor used in both human and canine studies, shows similar effectiveness in targeting the cellular pathways important in melanoma progression." (PMID 39408717, 2024). "Herein, the role of CD133-dependent activation of PI3K/mTOR in the regulation of melanoma progression, drug resistance, and recurrence is reviewed." (PMID 38334632, 2024). "The PI3K-Akt-mammalian target of rapamycin (mTOR) pathway is intracellular and is aberrantly upregulated in different tumor types, including melanoma." (PMID 38334632, 2024). "Itraconazole, a commonly used antifungal compound, has been observed to impair the growth and colony-formation ability of melanoma cells by hampering the functions of the PI3K/mTOR, HH and Wnt intracellular signaling pathways." (PMID 39199632, 2024). "Our working group pioneered T-cadherin research in melanoma, and we were able to show that T-cadherin is a tumor suppressor lost in melanoma followed by increased activity of the PI3K/AKT/mTOR pathway." (PMID 38791932, 2024). "Inhibition of the PI3K/AKT/mTOR pathway was also found by another group studying lidocaine and 5-fluorouracil effects on melanoma cells." (PMID 38741694, 2024).
melanoma (continued). "Targeting NF1-regulated pathways such as RAS/MAPK or PI3K/mTOR offers potential therapeutic options for patients with melanoma." (PMID 38565978, 2024). "Abnormal activation of the PI3K/AKT/mTOR pathway in different tumor types including melanoma has been suggested as the key mechanism through which tumors evade drug toxicity." (PMID 38334632, 2024). "Dysregulated mTOR activity can be found in a variety of cancers, including prostate, breast, lung, melanoma, bladder, brain, and kidney cancers, leading to mTOR as a critical therapeutic target." (PMID 38755125, 2024). "This shortcoming of PI3K/AKT/mTOR inhibitors as therapeutic targets in melanoma treatment is attributed to feedback loops derived from the inhibition of PI3K/mTOR leading to the activation/reactivation of aberrant signaling pathways like RAS/RAF/MEK/ERK." (PMID 38334632, 2024). "Consistently, topotecan treatment decreased SIRT1 expression, phosphorylation of Akt at Ser473 and mTOR at Ser2448, as well as EMT activity, but had minimal effects in USP22‐deficient melanoma cells." (PMID 39135915, 2024). "The phosphatidylinositol 3-kinase (PI3K)/AKT and mammalian target of rapamycin (mTOR) signaling pathways, which are often activated in melanoma, play a crucial role in conferring resistance to targeted therapy, immunotherapy, and chemotherapy." (PMID 38921444, 2024). "Previous studies have highlighted that HIF-1α can affect the progression of melanoma through the PI3K/AKT/mTOR signaling pathway, and celastrol has been demonstrated to inhibit the growth of melanoma cells by inhibiting PI3K/AKT signaling." (PMID 38771435, 2024). "The PI3K/Akt/mTOR pathway is a crucial signaling cascade involved in various aspects of melanoma biology, including tumor growth, survival, metabolism, and therapeutic resistance." (PMID 39200315, 2024). "Previous research shows that UCP2 promotes tumorigenesis via enhancing the Akt/mTOR pathway in melanoma." (PMID 38217303, 2024). "Altering redox homeostasis by increasing oxidative stress in melanoma cells inhibited PI3K/AKT/mTOR signalling by disrupting mTORC1 formation, thereby reducing colony formation and cell proliferation." (PMID 39594467, 2024). "More importantly, targeting the PI3K/AKT/mTOR signaling pathway has demonstrated the ability to inhibit the proliferation and migration of melanoma cells." (PMID 38771435, 2024). "Skin cancer is divided into various types, represented as melanoma and keratinocyte carcinoma, depending on the area it occurs and its relationship to the mTOR pathway." (PMID 39349424, 2024). "Resistance-mediating processes include the phosphorylation of ribosomal protein S6 (pS6), which is downstream of MET and mTOR signaling and was observed in progressive BRAFi-resistant melanomas." (PMID 38386085, 2024). "The serine–threonine kinase 1 (AKT1)/mammalian target of rapamycin (mTOR) axis is involved in melanoma progression." (PMID 37539493, 2023). "In 2020, Gong and Xia found that resveratrol affects the viability and migration of A-375 melanoma cells by suppressing the AKT/mTOR pathway, thus triggering autophagy." (PMID 36829966, 2023). "PYCR2 indispensable for the regulation of energy metabolism, and studies have reported that PYCR2 silence activates AMPK/mTOR pathway induced autophagy in melanoma can regulate downstream genes through the AMPK/mTOR pathway." (PMID 37325047, 2023). "Kaempferol demonstrated significant anticancer effects on A375 human melanoma cells via induction of apoptosis, suppression of cell migration, inhibition of cell cycle arrest, and targeting of the mTOR/PI3K/AKT pathway." (PMID 36829966, 2023). "MEL, the peptide component of BV, has been re-ported to suppress the growth and migration of melanoma cells via MEL-induced inhibition of the PI3K/AKT/mTOR pathway and MAPK pathways." (PMID 37098530, 2023).